LY6D (lymphocyte antigen 6 family member D)
Diseases named in the same sentence as LY6D in open-access papers (continued):
Sharing a sentence is not in itself a finding about the gene and the disease.
tumor (continued). "The results, based on analyses of tumours from three independent patient cohorts, confirm a strong link between LY6D expression and differentiation grade." (PMID 33042546, 2020). "Many of the genes upregulated in these tumor initiating cells were expressed in our Cluster 1 cells including Tff3, Tspan8, Gpc3, Ly6d, Cldn2." (PMID 33173221, 2020). "In both cohorts, LY6D expression was significantly higher in low-grade tumours, and in tumours with lower T-stages." (PMID 33042546, 2020). "Notably, CALU, TFRC, and GBP2 were highly expressed in early developmental stages, whereas SERPINB5 and LY6D were up-regulated in later phases, indicating their involvement in distinct stages of cellular state transitions and tumor progression." (PMID 41595468, 2025). "In the tumor microenvironment, LY6D may indirectly influence the tumor immune microenvironment by regulating the expression of key enzymes or transporters in the taurine metabolic pathway." (PMID 40230840, 2025). "We first asked whether the relationship among ATRX, HNF4A, CDX2 and LY6D expression identified in our mouse model exists in human tumour samples." (PMID 40468074, 2025). "Moreover, consistent with a role for ATRX, HNF4A and CDX2 in maintaining lineage fidelity and suppressing squamous-like plasticity, we observed low expression of these proteins in tumours containing LY6D+ cells." (PMID 40468074, 2025). "Their high-level influence on the tumor's interaction with the host immune system suggests that further study of these targets could yield novel therapeutic approaches, such as enhancing anti-tumor immunity by targeting LY6D or restoring SLURP1 function." (PMID 40740240, 2025). "Considering this background, LY6D may indirectly interfere with immune regulatory networks dependent on or triggered by BA activation, potentially reducing the anti-tumor effects mediated by BA." (PMID 41595468, 2025). "Finally, the quantification of two members of the Ly6 family - Ly6D and Ly6K - was performed in 5 human tumor cell lines." (PMID 38356711, 2024). "Interestingly, the LY6D+ SMO inhibitor-resistant tumor cells, extensively cover the morphological and transcriptional cell states of basal to squamous cell carcinoma transition." (PMID 39558960, 2024). "Additionally, we found a proliferative TREM2+VCAM1+ macrophage primarily residing in the LT region (which we termed SCAMs) that possesses the surprising capacity to directly regulate LY6D- tumor epithelial proliferation via the secretion of OSM ligand." (PMID 37164949, 2023). "Furthermore, CellChat predicted that the signaling from SCAMs to the tumor epithelium was specifically to the Ly6d- cells, supporting our observations in our SCAM and organoid add-back experiments." (PMID 37164949, 2023). "To determine whether LY6D has a functional role beyond its clear utility as a biomarker of squamous states, we utilized our tumor organoid model and introduced anti-Ly6d antibodies." (PMID 36473848, 2022). "Compared to normal tissue, LY6D levels were higher in the tumor tissue of CESC, LUSC, and PAAD." (PMID 36473848, 2022). "Importantly, this growth advantage was specific to tumor Ly6d+ cells as Ly6d+ cells from the normal epidermis were growth-arrested compared to normal Ly6d− cells." (PMID 36473848, 2022). "Roughly 11 of the 24 (45.8%) scRNA-Seq tumor datasets analyzed here have higher levels of LY6D, suggesting that ASCP might be more widespread than initially thought." (PMID 36473848, 2022). "Furthermore, we noted that tumor ductal cells with higher levels of LY6D had a higher persister score, raising the possibility of a similar squamous-associated state observed in BCCs." (PMID 36473848, 2022). "In addition, our studies rely on previous work to identify signaling pathways that can also influence LY6D+ tumor accumulation." (PMID 36473848, 2022).
tumor (continued). "It is interesting to draw parallels between the LY6D+ cell in BCCs and whether they can potentially serve as SCC cancer stem cells (CSCs), giving rise to the SCC-associated tumor epithelium observed in multiple contexts such as rBCCs and BSCs27." (PMID 36473848, 2022). "Along with tumor size, drug therapy also affects the proportion of LY6D+ cells." (PMID 36473848, 2022). "However, the finding of a significantly lower expression of LY6D in primary tumours from cystectomy specimens than from paired TURB specimens, in particular in patients who had not received NAC, merits some attention." (PMID 33042546, 2020). "This difference may well be due to the fact that all analyses in the present study are based on tissue microarrays, which may render some false negative results given the inherent heterogenous staining pattern of LY6D denoted in some of the tumours." (PMID 33042546, 2020). "LY6D was expressed in the cytoplasm and cell membrane of tumour cells." (PMID 33042546, 2020). "We found that Ly6d and SCA-1 show similar expression patterns in our model system, and our observation that knockdown of Ly6d expression significantly attenuated the colony-forming ability of KC and AC cells suggested that Ly6d plays a key role in the self-renewal of tumor cells." (PMID 33348616, 2020). "Moreover, LY6D expression was also found to be higher in tumours with squamous differentiation than in tumours with classic urothelial histology or in tumours with other variant histologies." (PMID 33042546, 2020). "It would also be of interest to examine whether LY6D is a predictive marker of chemoresistance in tumours from a randomized trial, as the real-world setting of the herein studied MIBC cohort does not allow for more than cautious speculations in this regard." (PMID 33042546, 2020). "LY6D is involved in coordinating multiple immune processes, including T-cell and B-cell activation, dendritic cell maturation, neutrophil and natural killer cell responses, and macrophage polarization, suggesting its potential role in shaping the tumor immune microenvironment." (PMID 41595468, 2025). "Furthermore, our work highlights the therapeutic implications of targeting LY6D itself may have functional roles, but additional considerations are needed to target tumor-specific LY6D+ cells." (PMID 36473848, 2022). "LY6D may modulate the expression of the Taut, thereby affecting the uptake of taurine by tumor cells, altering the intracellular taurine levels in tumor cells, and ultimately influencing the proliferative, survival, and immune escape capabilities of tumor cells." (PMID 40230840, 2025). "Immunohistochemistry images from the HPA database also manifested that the protein expression levels of ANLN, LY6D, and SERPINB3 are notably higher in PC tumor tissues." (PMID 41427028, 2025). "By the GEPIA platform, we conducted an expression analysis at the RNA level and discovered significant upregulation of SERPINB3, LY6D, DCBLD2, and ANLN within PC tumor tissues." (PMID 41427028, 2025). "Reduced production of the Ly6D and Ly6K proteins was shown after ASPH inhibition in human tumor cell lines." (PMID 38356711, 2024). "likewise, IHC staing affirmed that the protein expression patterns of LY6D, MET, MUC16, and WNT7A were increased in tumor sample compared to healthy samples." (PMID 38169540, 2024). "Among these genes, the expression of LY6D, SCNNA1, TSPAN1 and RECQL was significantly higher in tumor tissues than in normal tissues, but the expression of TSPAN1 and RECQL was significantly lower in tumor tissues than in normal tissues." (PMID 37274269, 2023). "The expression of LY6D, SCNNA1 and TSPAN1 was higher in tumor tissues than in normal tissues, whereas the expression of RECQL, PEG10 and SEPT3 was lower in tumor tissues than in normal tissues." (PMID 37274269, 2023).
tumor (continued). "We also validated the differential expression of LY6D and HPDL using Western blot analysis, which confirmed that they were expressed at higher levels in tumor tissues." (PMID 37274269, 2023). "To understand the spatial localization of TREM2+ cells in relation to the different tumor epithelial states, we co-stained for TREM2 and LY6D in human BCCs." (PMID 37164949, 2023). "LY6D, LY6E, PLAUR, PSCA, CD59 and LYPD3 mRNA expression was significantly increased in the PDAC tumor tissues than normal adjacent tissues (p < 0.01)." (PMID 33613843, 2021). "Consequently, when tumours with squamous differentiation, but not other variant histologies, were excluded from the survival analyses, the prognostic value of LY6D was found to be somewhat enhanced for the category with the highest expression, although still not reaching significance." (PMID 33042546, 2020). "To examine the possible effect of Ly6d expression on tumor aggressiveness in LUAD patients, we first performed immunohistochemical analysis of microarrays containing tumor tissue from 120 such individuals." (PMID 33348616, 2020). "Specifically, the level 3 classifier shows strong correlations among genes like KRT5, S100A7, KRT16, S100P, and LY6D, while the level 6 classifier exhibits similar patterns with GPR17, RGR, and NPPA, highlighting the complex interplay of genes in tumor subtype classification." (PMID 40802546, 2025). "Furthermore, we analyzed the protein expression levels of ANLN, DCBLD2, LY6D, and SERPINB3 using the UALCAN platform, which were notably upregulated within PC tumor tissues." (PMID 41427028, 2025). "LY6D and GBP2 are primarily involved in regulating immune cells and advancing the tumor cell cycle." (PMID 41595468, 2025). "Furthermore, the mRNA expression levels of FAM83A, LY6D, MET, MUC16, MYEOV, and WNT7A were elevated in PAAD tissues, while the protein expression patterns of LY6D, MET, MUC16, and WNT7A were higher in tumor sample." (PMID 38169540, 2024). "Mechanically, AP-1 and TGF-ß cooperativity drive the nuclear myocardin-related transcription factor (nMRTF) resistance pathway, which amplifies non-canonical GLI1 activity in the LY6D+ resistant tumor cells." (PMID 39558960, 2024). "In contrast, SCAMs appear not to enhance proliferation among LY6D+ tumor cells in more central portions of tumor nodules and segregated away from the tumor stroma." (PMID 37164949, 2023). "Furthermore, compared with those of the LC or KC mouse group, the tumor tissues of the KLC mouse group exhibited elevated HCC markers (Cd44, Afp, Gpc3 and Ly6d) (P < 0.001 or P < 0.01)." (PMID 38124228, 2023). "Conversely, rBCCs without SCC-like features lack LY6D expression but maintain GLI1 levels throughout the tumor." (PMID 36473848, 2022). "Third, to functionally confirm that the transition from an LY6D− to LY6D+ state is tumor cell-autonomous and spontaneous, we generated an SMOi-sensitive mouse BCC organoid system to culture bulk or sorted populations of tumor epithelial cells based on specific surface markers." (PMID 36473848, 2022). "We conclude that despite the spontaneous suprabasal conversion from LY6D− to LY6D+ tumor cells, LY6D+ BCC cells do not exit the cell cycle and maintain their proliferative potential." (PMID 36473848, 2022). "Using four scRNA-Seq clusters defined by both normal and BCC cells as well as LY6D− and LY6D+ fractions (Normal: LY6DLow, Normal: LY6DHi, Tumor: LY6DLow, and Tumor: LY6DHi), we were able to impute and integrate these clusters onto the scATAC-Seq clustering for subsequent analysis." (PMID 36473848, 2022). "Furthermore, basosquamous regions were typically found 2–3 cells away from the BMZ, suggesting that overall tumor size, intratumor nodular size, and distance from the BMZ contribute to LY6D/Ly6d levels." (PMID 36473848, 2022).
tumor (continued). "Consistent with the observed increased proliferative differences, we noted prominent Mki67+/Ly6d+ cells in our mouse scRNA-Seq data and subsequently found Edu incorporation of Ly6d+ cells from the tumor are more significant than from the normal epidermis." (PMID 36473848, 2022). "Consistent with the low SMO activity driving LY6D+ accumulation, human rBCCs containing high levels of SMO activity through activating mutations lacked spontaneous LY6D+ tumor accumulation." (PMID 36473848, 2022). "LY6D expression was however not prognostic in separate analysis of tumours with classic urothelial histology only." (PMID 33042546, 2020). "Of note, in Cohort II, but not in Cohort I, LY6D expression was significantly higher in tumours of female patients than in male patients." (PMID 33042546, 2020). "In Cohort III, the expression of LY6D could be assessed in 144 (99.1%) TURB specimens, in 101 (74.8%) tumours from the cystectomy specimens, and in 23 (85.1%) lymph node metastases." (PMID 33042546, 2020). "We could rescue Ly6d− tumor organoid growth by adding SCAMs, whereas the addition of SCAMs did not affect Ly6d+ organoid growth." (PMID 37164949, 2023). "As the tumor and tumor nodules grow, the distance from the characteristic BCC tumor stroma becomes larger, suggesting that lack of stroma (its contact and/or secreted factors) may drive towards an LY6D+ state." (PMID 36473848, 2022). "However, in contrast to the mixed cohorts, LY6D expression was found to be significantly higher in T4 compared to T2 tumours in the TURB specimens, but not in the cystectomy specimens." (PMID 33042546, 2020). "LY6D expression was generally lower in the MIBC cohort, and even more reduced in resected tumours compared to TURB specimens in patients who had not received neoadjuvant chemotherapy." (PMID 33042546, 2020). "While we have shown that LY6D+ BCCs lack HH/GLI signaling, form spontaneously without treatment, and remain proliferative compared to normal tissue, we further investigated the determinants affecting LY6D+ tumor cell accumulation." (PMID 36473848, 2022).
cancer (25 papers, 2016 to 2025). A tumor composed of atypical neoplastic, often pleomorphic cells that invade other tissues. "Inhibition of the tripartite motif-containing 24 protein (Trim24), which has been reported as a suppressor of lipid accumulation and cancer development in the liver, was most significantly associated with Ly6d expression." (PMID 37394588, 2023). "LY6D is a GPI-anchored member of the LY6 family with a recently established association with aggressive cancers and poor patient outcome." (PMID 33613843, 2021). "In addition to Fos, some other genes associatedwith cancer, such as Anxa1, Samd9, Tppp3, Slc22a3, and Ly6d, were differently regulated in both or one of the GX-rich groups,compared with the control group." (PMID 38343302, 2024). "LY6D plays an important role in lymphocyte differentiation, cell adhesion, cancer progression and immune escape." (PMID 38513301, 2024). "In recent years, it has been found that LY6D has increased expression in some type of cancers and is related to cell adhesion." (PMID 38067506, 2023). "A recent single-cell sequencing study pointed out that Ly6d was a marker for castration-resistant prostate luminal cells and cancer development." (PMID 35841025, 2022). "Overall, this work highlights that LY6D is expressed in multiple cancers and can be targeted, suggesting that LY6D has functional relevance beyond a biomarker." (PMID 36473848, 2022). "P25 TRAMP CRIPSCs also had upregulated genes related to cancer development and drug resistance, such as Aldh3a1, Ly6d, Il33, Dsg3, and Col17a1." (PMID 35841025, 2022). "Recently, several studies have shown the correlation between LY6D expression level and poor patient outcomes in multiple cancer types such as breast, lung, gastric, ovarian, and prostate and other carcinomas." (PMID 33168631, 2021). "Given the similarity between cancer and senescent cells in terms of the high metabolic activity, it is possible that LY6D-induced macropinocytosis contributes to meet the increased energy demand of senescent cells." (PMID 33168631, 2021). "To examine the status of Ly6D in human cancer, we used Oncomine or G-DOC to analyze gene expression omnibus (GEO) datasets." (PMID 26862846, 2016). "Besides LY6A/LY6S, other LY6 family members have been suggested as close homologues of the murine Ly6a gene, such as LY6D, LY6E, LY6H and LY6K, which were implicated as biomarkers for poor cancer prognosis and are frequently amplified in human cancer." (PMID 39642167, 2025). "In addition, with the use of these models, we identified Ly6d as a potential novel cancer stem cell marker for LUAD." (PMID 33348616, 2020). "Increased expression of Ly6D, Ly6E, Ly6H or Ly6K was observed in sub-set of cancer type." (PMID 26862846, 2016). "Besides, these genes, ADAMTS2, KRT9, KRT13, LY6D, had been reported in a variety of cancers." (PMID 35237592, 2022). "mRNA expression of FAM83A, LY6D, MET, MUC16, MYEOV, and WNT7A were significantly elevated in cancer than healthy tissues (P<0.05)." (PMID 38169540, 2024). "LY6D is a member of the 10-gene signature, and recent studies have shown that human LY6 genes are related to poor prognosis and play a crucial role in cancer progression and immune escape." (PMID 37274269, 2023). "The results showed that BCAT1, LY6D, and ITGB6 were significantly overexpressed in cancer tissues." (PMID 34976806, 2021). "Of note, LY6D, ST3GAL4, ASS1, PTP4A3 (also named PRL-3), UBE2C (also named UBCH10), and E2F3 are novel oncogenes and biomarkers whose overexpression are related to metastases, migration, or proliferation of NSCLC and other cancers." (PMID 27935865, 2017). "The mechanism of FAM57B and LY6D in malignant tumors has not been reported." (PMID 36595826, 2022).
infection (1 paper, 2023). The state of being infected such as from the introduction of a foreign agent such as serum, vaccine, antigenic substance or organism. "In this purview, the presence of infection-associated proteins (GUSB, GZMB, LEAP2, LY6D) in estrus urine is interesting." (PMID 37104448, 2023).
LY6D also shares sentences with these, for which no sentence is quoted: liver (2 papers); adenoid cystic carcinoma (1); cervical squamous cell carcinoma (1); endocervical adenocarcinoma (1); esophageal carcinoma (1); lung adenocarcinoma (1); lung squamous cell carcinoma (1); lymph node metastases (1); non-small cell lung carcinoma (1); nonalcoholic fatty liver disease (1); osteosarcoma (1); pancreatic ductal adenocarcinoma (1); renal clear cell carcinoma (1); resistant hypertension (1); rhabdoid tumor (1); Stroke (1).